CECR7 (cat eye syndrome chromosome region, candidate 7)
Synonyms: SAHL1
Gene: Transcribed unprocessed pseudogene on chromosome 22 (17,044,873 to 17,047,426, forward strand). Ensembl gene ENSG00000237438.
Diseases named in the same sentence as CECR7 in open-access papers:
CECR7 is named in the same sentence as 7 diseases in open-access papers, as found by Europe PMC text mining. Sharing a sentence is not in itself a finding about the gene and the disease. The quoted sentences say what the papers report.
cat-eye syndrome (4 papers, 2015 to 2024). Cat eye syndrome (CES) is a rare chromosomal disorder with a highly variable clinical presentation. "Among the three risky lncRNAs, CECR7 is a candidate lncRNA for Cat Eye Syndrome." (PMID 26492393, 2015).
hepatocellular carcinoma (1 paper, 2019). A malignant tumor that arises from hepatocytes. "lncRNA CECR7 interacts with mir-377 and had been reported to play a role in hepatocellular carcinoma." (PMID 32010179, 2019).
pancreatic cancer (1 paper, 2022). "A ceRNA network profile has identified the several lncRNAs for classifying diabetic pancreatic cancer form non-diabetic pancreatic cancer, including HOTAIR, CECR7, UCA1, suggesting that lncRNAs are important predictors for diabetic pancreatic cancer." (PMID 36313695, 2022).
cancer (1 paper, 2015). A tumor composed of atypical neoplastic, often pleomorphic cells that invade other tissues. "Repressive chromatin-associated lncRNAs also includeseveral lncRNAs (PCA3, GAS6-AS1, CECR7 and BDNF-AS1)that have been implicated in cancer or other cellular functions, and among thisBDNF-AS1 lncRNA has been shown to regulate gene expression by recruitingPRC2 (refs 30, 52,53, 54)." (PMID 26205790, 2015).
CECR7 also shares sentences with these, for which no sentence is quoted: gastric cancer (1 paper); resistant hypertension (1); tumor (1).